NME1 (NME/NM23 nucleoside diphosphate kinase 1)
Diseases named in the same sentence as NME1 in open-access papers (continued):
Sharing a sentence is not in itself a finding about the gene and the disease.
colorectal cancer (21 papers, 1993 to 2025). A primary or metastatic malignant neoplasm that affects the colon or rectum. "Association between NME1 polymorphisms and the 5-year disease-free survival of colorectal cancer patients." (PMID 40417235, 2025). "Association between NME1 polymorphisms and the 5-year overall survival of colorectal cancer patients." (PMID 40417235, 2025). "The aims of this study were to evaluate the contribution of two polymorphisms of NME1 to the risk of colorectal cancer (CRC) development and the clinical outcomes of CRC patients in a northern Chinese population." (PMID 40417235, 2025). "Consistent with this, NME1 expression is strongly reduced or lost at the invasive front of human colorectal carcinoma, which is close to the stroma and where EMT takes place in these tumors." (PMID 33918324, 2021). "There were 7, 5, 4 and 1 studies reporting the data of NME1 expression and overall survival (OS) of the patients with colorectal cancer, gastric cancer, esophagus cancer and pancreatic cancer, respectively." (PMID 27518571, 2016). "Our study elucidates the potential pro-tumor mechanism of NUhighepi and the role of NME1 in inhibiting metastasis, further deepening the understanding of the role of nucleotide metabolism in colorectal cancer, and providing valuable targets for disrupting its properties." (PMID 39075485, 2024). "Thus, we propose that miR‐210 regulates the degradation of XIST in cells as a mechanism to promote colorectal cancer and reducing NME1 expression." (PMID 36116139, 2022). "NME1 expression might be regulated by microRNA: it is reported, for example, that miR-28-3p downregulates NME1 in colorectal cancer cells." (PMID 33918324, 2021). "In colorectal carcinoma (CRC), NME1 inhibits the myosin light chain (MLC), resulting in reduced cell migration." (PMID 39063217, 2024).
colon carcinoma (20 papers, 1993 to 2024). "Moreover, the loss of macrophage‐produced NME1 weakens the integrity of monolayers formed by CEC with deficient NME1, in line with the view that NME1 silencing disrupts cell–cell adhesion of human colon cancer cells." (PMID 36922750, 2023). "LOH mostly arose in the late period of sporadic colon cancer and endowed it with high aggressive and poor prognosis, while NME1 overexpression suppressed colon cancer metastasis and promoted prognosis of sporadic colon cancer patients, effectively." (PMID 27518571, 2016). "Negative regulation and worse prognosis of NME1 was also demonstrated in colon cancer." (PMID 32197468, 2020). "In addition, NME1 inhibits the liver metastasis of colon cancer cells by regulating the phosphorylation of myosin light chains in nude mice." (PMID 32977620, 2020).
lung carcinoma (20 papers, 2010 to 2025). "Second, it is necessary to investigate combined effects of β-catenin and NME1 on apoptosis, migration, invasion, or metastasis in different cell types of lung cancer to clearly understand the molecular mechanisms underlying the effect of β-catenin and NME1 on poor RFS." (PMID 32977620, 2020). "It responds to NME1 in high-metastatic lung cancer cell line L9981." (PMID 32977620, 2020). "The expression levels of GYPC, NME1 and SLIT2 in S30 cells and lung cancer cell lines were validated by quantitative PCR, immunofluorescence, and western blot assays." (PMID 32795291, 2020). "NME1 is also a negative regulator of TGF-β1, which promotes EMT in lung cancer." (PMID 39063217, 2024). "The role of NME1/2 in cancer is still controversial and not well-defined in colorectal, gastric, and lung cancers." (PMID 39063217, 2024).
lymph node metastasis (18 papers, 1993 to 2023). "When lymph node metastasis was considered, the mRNA expression level of NME1 was greater in N1 and N2 vs. N0." (PMID 32795291, 2020). "In this study, increased mRNA expression of NME1 was found to be related to LUAD invasion depth and lymph node metastasis." (PMID 32795291, 2020). "When comparing the primary two members of NM23 family, Tokunaga found that the expression of NME1, but not NME2, was inversely associated with lymph-node metastasis (p < 0.01)." (PMID 27518571, 2016).
ovarian carcinoma (18 papers, 1995 to 2025). A malignant neoplasm originating from the surface ovarian epithelium. "Low levels of NME1 expression have been linked to advanced stages of ovarian carcinoma and lymph node metastasis." (PMID 30158514, 2018). "Our regression analysis identified six genes significantly associated with ovarian cancer: PI3, TFAP2B, MUC7, PSMA2, PIK3C2G, and NME1." (PMID 41154754, 2025). "After transplanting eight ovarian cancer cell lines subcutaneously into the flank of nude mice, the expression of NME1 mRNA and protein in human ovarian cancer cells was inversely related to metastatic behavior in experimental animals (r = 0.96, P = 0.0001)." (PMID 27518571, 2016). "Moreover, TNPO1, ACLY, NME1, FLOT1, and KLC4 are proteins already known to be involved in epithelial ovarian cancer." (PMID 37775701, 2023).
gastric cancer (13 papers, 2007 to 2025). A primary or metastatic malignant neoplasm involving the stomach. "In conclusion, FABP5 and NME1 were not only identified as normal gastric corpus stem/progenitor markers, but also proven to be important for the propagation in gastric cancer cells." (PMID 37402315, 2023). "Importantly, FABP5 and NME1 were identified and validated as crucial for both normal gastric stem/progenitor cells and gastric cancer cells." (PMID 37402315, 2023). "In addition, the identified gastric stem/progenitor marker genes here, that is, FABP5 and NME1, are also important for the propagation in gastric cancers as proved by in vivo gastric cancer samples and several gastric cancer cell lines." (PMID 37402315, 2023). "Since FABP5 and NME1 were proven to be important for gastric epithelial stem/progenitor cells, we asked whether they also play a crucial role in gastric cancers." (PMID 37402315, 2023). "Thus, to test this hypothesis, we knocked down FABP5 and NME1 in seven different gastric cancer cell lines, including AGS, HGC-27, MGC-803, KATO III, NCI-N87, SNU-5, and SNU-16." (PMID 37402315, 2023). "Moreover, NME1 may act as a molecular switch between the free-floating and adherent states of gastric cancer cells." (PMID 27518571, 2016). "In all seven gastric cancer cell lines, either or both of FABP5 and NME1 knockdown would result in a significant reduction of proliferation, an increase of apoptosis." (PMID 37402315, 2023).
breast tumor (10 papers, 1996 to 2023). "As a consequence, loss of NME1 function enhances both matrix degradation and the invasive potential of breast tumor cells in vitro." (PMID 37353690, 2023). "We focus on a model of epithelial–mesenchymal transition induced by the loss of the metastasis suppressor NME1 in breast tumor cells." (PMID 36111347, 2022). "In two large databases of clinical and biological data on human breast tumors, NME1 expression was positively associated with expression of epithelial markers and negatively associated with expression of mesenchymal markers and EMT drivers." (PMID 33918324, 2021). "In order to explore the mechanism underlying the enhancement of breast tumor invasion by NME1 down-modulation, the cellular distribution of NME1 was examined." (PMID 34012098, 2021). "Together with the potent inhibition of the invasive switch caused by the loss of MT1-MMP in the intraductal model, these convergent findings suggested that the loss of NME1 function in breast tumor epithelial cells could unleash MT1-MMP proinvasive activity." (PMID 34012098, 2021). "Overexpression of NME1 in breast tumor cells was found to increase MT1-MMP endocytosis resulting in removal of the protease from the cell surface, whereas silencing of NME1 decreases MT1-MMP uptake." (PMID 37353690, 2023). "This inverse relationship between NME1 expression and metastatic potential is most strongly observed in breast tumors." (PMID 36111347, 2022). "NME1 levels drop in microinvasive and invasive components of breast tumor cells relative to synchronous DCIS foci." (PMID 34012098, 2021). "Knockout of NME1 accelerates the invasive transition of breast tumors in the intraductal xenograft model." (PMID 34012098, 2021). "The aim of this work was first to raise specific antibodies to allow the analysis of Nme1 and then, with this specific tool, to evaluate the predictive value of Nme1 detection in cytosolic extracts of human breast tumours." (PMID 8605098, 1996). "NME1 inhibited the actin depolymerizing activity of gelsolin, antagonized gelsolin-stimulated tumor cell migration in vitro, and attenuated its pro-metastatic activity in an in vivo model of breast tumor metastasis." (PMID 37353690, 2023). "In addition, the ability of NME1 to influence tumor invasion in vivo has been demonstrated in a xenograft model in which human breast tumor cells were injected into the primary duct of the mammary gland in immunodeficient mice." (PMID 37353690, 2023). "In a model of breast tumor cells genetically modified for NME1, we correlated tumor invasion, migration, and adhesion modifications with shape maintenance properties by measuring surface tension and exploring both invasive and migratory potential as well as adhesion characteristics." (PMID 36111347, 2022). "Moreover, we explore the role of both NME1 and NME2 in such metastasis-associated biological processes as EMT, migration, and invasion by using a breast tumor cell line model." (PMID 36111347, 2022). "We found that NME1 expression was negatively associated with EMT markers in many human cancers and was reduced in human breast tumor cell lines with the aggressive ‘triple-negative’ phenotype when compared to human breast tumor cell lines positive for estrogen receptor." (PMID 33918324, 2021). "We observed a striking anti-correlation of cortical MT1-MMP and NME1 both in DCIS and IBC breast tumor counterparts." (PMID 34012098, 2021). "Here, we investigated the expression of NME1 and NME2 in synchronous DCIS and IBC foci in breast tumors." (PMID 34012098, 2021). "Given the up-regulation of MT1-MMP during the in situ-to-invasive transition in relation with poor clinical outcome, we compared NME1 and MT1-MMP levels in the breast tumor cohort." (PMID 34012098, 2021). "We find a strong anti-correlation between NME1 and plasma membrane MT1-MMP levels in the invasive components of breast tumors, particularly in aggressive histological grade III and triple-negative breast cancers." (PMID 34012098, 2021).
breast tumor (continued). "Other up-regulated proteins of interest with possible roles in regulating breast tumor cell progression included DPYSL2, FAM129B, IL18, NDRG1, NME1, and SERPINB5." (PMID 28174229, 2017). "Collectively, these data indicated that the loss of NME1, but not of NME2, accelerated the invasive switch of breast tumors in the intraductal xenograft assay, possibly in relation with increased plasma membrane MT1-MMP levels." (PMID 34012098, 2021). "We observed significantly more NME1 mRNA in the ER-positive human breast tumor cell lines than in the normal-like cell lines; these levels significantly decreased in the triple-negative human breast tumor cell lines, reaching a similar level to that observed in normal-like cell lines." (PMID 33918324, 2021).
metastatic carcinoma (8 papers, 2008 to 2024). A carcinoma which has spread from the original site of growth to another anatomic site. "Nme1, a potential target for metastatic cancer gene therapy, was also significantly up-regulated (x = 1.30, CUT = 1.26)." (PMID 38534766, 2024). "This could be because both cell lines are highly invasive and have a lower level of NME1 compared to low-metastatic carcinoma cells." (PMID 35259022, 2022). "We do not know yet how NME1 expression is reduced or lost in invasive and metastatic cancer cells." (PMID 33918324, 2021).
lung adenocarcinoma (7 papers, 2011 to 2025). A carcinoma that arises from the lung and is characterized by the presence of malignant glandular epithelial cells. "NME1 was shown to be decreased 2.2-fold in lung adenocarcinoma in the present study." (PMID 22087286, 2011). "Compared with normal BEAS-2B cells, the expression levels of GYPC and SLIT2 in four human lung adenocarcinoma cell lines (PC9, A549, H1975 and H1299) were up-regulated, while NME1 expression was down-regulated." (PMID 32795291, 2020).
metastatic disease (7 papers, 2008 to 2021). "Similarity NME/NM23 nucleoside diphosphate kinase 1 (NME1) mapping in 17q21.3, has been also found overexpressed in some NBs and the upregulation correlated with metastatic disease." (PMID 26358114, 2015).
prostate carcinoma (7 papers, 2007 to 2024). A carcinoma that arises from epithelial cells of the prostate gland. "The study’s findings suggest that the downregulation of NME1 may be associated with advanced prostate cancer and might contribute to the aggressive behavior of the disease." (PMID 38201450, 2023). "Their investigation indicated that NME1 could be used as a diagnostic and prognostic indicator, adding further support to its relevance in understanding prostate cancer progression." (PMID 38201450, 2023). "Importantly, high expression of NME1 was associated to a worse disease-free survival in prostate cancer patients in the TCGA dataset, and high SHMT2 expression in the TCGA and the Glinsky datasets." (PMID 33917317, 2021). "Further examination in publicly available prostate cancer transcriptome datasets confirmed NME1 and SHMT2 as consistently upregulated in prostate tumor cohorts." (PMID 33917317, 2021). "Also, expression of NME1 and SHMT2 is linked to poor prognosis in cancer patients, and in prostate cancer cells succinate enhances their expression." (PMID 33917317, 2021). "Another biomarker in our meta-analysis called NME1, also known as non-metastatic cells 1 protein, has been examined for its potential role as a biomarker in prostate cancer." (PMID 38201450, 2023).
colorectal tumours (6 papers, 1994 to 2025). "In colorectal tumor tissues, the expression of NME1 was shown to be low, and reduced NME1 was associated with higher Dukes stages, poorer differentiation, and positive lymph node metastases in CRC patients." (PMID 40417235, 2025). "A number of known or putative tumour-suppressor genes including NF1, BRCA1, NME1, NME2 and prohibitin are present on the long arm of chromosome 17, and this region has not been extensively analysed in colorectal tumours." (PMID 7734302, 1995).
invasive breast carcinoma (6 papers, 2014 to 2022). A carcinoma that infiltrates the breast parenchyma. "However, NME1’s implication in local invasion at the in situ-to-invasive breast carcinoma transition has been overlooked, and the mechanisms underlying metastasis suppression by NME1 remained largely unknown." (PMID 34012098, 2021). "As a model, we used human invasive breast carcinoma cells overexpressing NME1 or NME2, and first analysed in detail the presence of both isoforms in EV subtypes by capillary Western immunoassay (WES) and immunoelectron microscopy." (PMID 36010906, 2022). "We observed similar significant associations between levels of NME1 mRNA and mRNAs for markers of EMT in the TCGA database of 1100 human breast invasive carcinoma samples." (PMID 33918324, 2021). "Anti-correlation of NME1/MT1-MMP levels was confirmed in RNAseq data in invasive breast carcinoma (TCGA, not shown)." (PMID 34012098, 2021). "Furthermore, a negative association between NME1 and ADAM10 protein levels was observed in 74 samples of breast invasive carcinoma in the TCGA database by mass spectrometry." (PMID 33918324, 2021).
osteosarcoma (6 papers, 2017 to 2022). A usually aggressive malignant bone-forming mesenchymal neoplasm, predominantly affecting adolescents and young adults. "A recent report shows that NME1 is required for NHEJ activity in osteosarcoma U2OS cells." (PMID 32824412, 2020). "NME1 has also shown to enhance total NHEJ activity in A549 (lung adenocarcinoma), U2-OS (osteosarcoma) and HEK293 (embryonic kidney) cells but was reported to exert no impact on HR activity." (PMID 32824412, 2020).
liver cancer (5 papers, 2015 to 2024). An epithelial or non-epithelial malignant neoplasm that arises from the liver. "After analyzing six tumor-specific signatures (IDI1, GMPPA, NME1, PSMB3, SPTLC1 and EBP), the gene effect and gene dependency were measured in different non-cancerous cell lines and liver cancer lines of human HCC." (PMID 38927057, 2024).
pancreatic cancer (5 papers, 2008 to 2021). "Several studies support our findings, showing that NME1 is highly expressed in pancreatic cancer samples and predicts worse prognosis in patients." (PMID 32197468, 2020).
thyroid cancer (5 papers, 1993 to 2017). "McCorkle investigated NME1-regulated gene expression in WM1158 and WRO82 cells and found that a number of genes regulated by NME1 in melanoma and thyroid carcinoma cell lines would become potential predictors of survival in breast cancer." (PMID 27518571, 2016).
chronic myelogenous leukemia (4 papers, 2012 to 2019). "Another study showed that stably-transfected chronic myeloid leukemia K562 cells, expressing RNAi for post-transcriptional silencing of Nme1 gene, exhibited a markedly increased ability to form colonies in terms of number and size compared to the control." (PMID 31877804, 2019).
ductal carcinoma in situ (3 papers, 2021 to 2023). "For this, we compared three different cell lines: ductal breast carcinoma in situ that are considered control tumor cells and two derivative cell lines obtained by inactivation of either NME1 or its closely related isoform NME2." (PMID 36111347, 2022). "Here, we report that NME1 is up-regulated in ductal carcinoma in situ (DCIS) as compared to normal breast epithelial tissues." (PMID 34012098, 2021).
oral squamous cell carcinoma (3 papers, 2004 to 2020). "In particular, NME1 was reported increased by cigarette smoking in oral squamous cell carcinoma (OSCC), and the lower expression of SLIT2 were found in the lungs of cigarette smoke-induced emphysema mice." (PMID 32795291, 2020).
Parkinson disease (3 papers, 2020 to 2023). A progressive degenerative disorder of the central nervous system characterized by loss of dopamine producing neurons in the substantia nigra and the presence of Lewy bodies in the substantia nigra and locus coeruleus. "The researchers concluded that NME1 improves mitochondrial function, which is disturbed in Parkinson’s disease, and should be considered as a potential therapeutic factor for axonal protection." (PMID 36768287, 2023).